S100A8 (S100 calcium binding protein A8)
Diseases named in the same sentence as S100A8 in open-access papers (continued):
Sharing a sentence is not in itself a finding about the gene and the disease.
Sepsis (continued). "The concentrations of S100A8/A9 and resistin in sepsis patients were noticeably increased relative to non-sepsis patients and healthy controls." (PMID 40568710, 2025). "Most importantly, the role of S100A8/A9 in predicting 28-day mortality from sepsis was validated in an additional 55 adult patients with sepsis." (PMID 40568710, 2025). "For example, the circulating S100A8/A9 level is highly increased in the blood of patients with sepsis." (PMID 40860162, 2025). "In conclusion, the present study demonstrates that T0 enhances LXRα and further protects against sepsis-induced lung injury via S100A8, which is a component of the autophagy-related pathway." (PMID 40994643, 2025). "Sepsis patients with high serum S100A8/A9 concentrations (≥ 377.53 ng/mL) had a higher survival rate relative to those with low concentrations (<377.53 ng/mL)." (PMID 40568710, 2025). "Survival curve analysis revealed that sepsis patients with lower serum S100A8/A9 levels at admission had reduced survival rates compared to those with higher levels." (PMID 40568710, 2025). "Among these, we found certain S100 family proteins (i.e. S100A12 and S100A11) exclusively elevated in sepsis samples, while traditional pro-inflammatory S100A8 and S100A9 were similarly expressed in both healthy and sepsis samples." (PMID 40965975, 2025). "As a result, serum S100A8/A9 concentrations are elevated in sepsis patients, consistent with previous findings." (PMID 40568710, 2025). "A previous study showed that S100A8/A9 were predictive markers based on serum samples of patients with sepsis." (PMID 40792106, 2025). "Although S100a8/a9 has been reported to trigger endothelial cell apoptosis, the mechanisms of S100a8/a9-induced endothelial dysfunction during sepsis require in-depth research." (PMID 38942784, 2024). "In macrophages, the most differentially expressed genes after sepsis include S100a9, S100a8, Hbb-bs, Fth1, AW112010, Spic, Cxcl2, Cd14, Hmox1, and Vcam1." (PMID 38343542, 2024). "H-MDSCs also share substantial overlap with M-MDSCs, with higher expression in sepsis of genes like S100A8/9 and DNAH17." (PMID 38720891, 2024). "Moreover, based on comprehensive scRNA-seq and bulk RNA-seq analyses, S100A8/A9hi neutrophils are closely associated with the circulating endothelial cell count (a useful marker of endothelial damage), and S100A8 is an independent risk factor for poor prognosis in sepsis patients." (PMID 38942784, 2024). "These clusters are expanded in CLP and have higher expression of S100A8/9 as evident by DEGs analysis in the spleen of sepsis-surviving mice." (PMID 39506629, 2024). "Inhibiting S100a8/a9 was a promising therapeutic approach to mitigate the development of SIC in sepsis patients." (PMID 39267971, 2024). "The present study demonstrated S100A8/A9 aggravated sepsis-induced pulmonary inflammation, vascular permeability, and lung injury." (PMID 37978525, 2023). "Our results identify S100A8/A9 as a potential marker of cardiac dysfunction in sepsis patients and promote systemic S100A8/A9 blockade as a viable treatment to ameliorate SIMD and improve patient prognosis." (PMID 37773186, 2023). "To determine the expression of S100A8/A9 in the livers of CLP-treated mice, we first established a sepsis-associated ALI model via CLP." (PMID 36768433, 2023). "Key genes upregulated during sepsis, including S100A8, S100A9, and CR1, are responsible for cell cycle regulation and immune responses." (PMID 37298316, 2023). "It is well-established that the calgranulin S100A8/A9 complex is one of the biomarkers in sepsis and exerts its inflammatory role through TLR4 activation." (PMID 37623960, 2023). "Both pharmacological inhibitions using paquinimod and genetic ablation of the S100A8/A9–TLR4 signaling axis improved survival in mice with CLP‐induced sepsis by suppressing platelet pyroptosis." (PMID 36852778, 2023).
Sepsis (continued). "In the present work, we investigated the relationship between systemic S100A8/A9 release and myocardial dysfunction in a cohort of patients with severe sepsis treated in the intensive care unit (ICU)." (PMID 37773186, 2023). "Second, the precise mechanisms involved in S100A8/A9 up-regulation in the lungs during sepsis and its crosstalk with the STAT3 and P38/ERK signalling pathways warrant further investigation." (PMID 37978525, 2023). "Our data support an interdependent relationship between elevated S100A8/A9, systemic inflammatory response and development of cardiac dysfunction in sepsis, and demonstrate that pharmacologic S100A8/A9 blockade reverses the detrimental phenotype." (PMID 37773186, 2023). "The present study is the first to establish that STAT3 signalling is regulated by S100A8/A9 in the lungs of CLP-operated mice, suggestive of a new molecular mechanism underlying sepsis." (PMID 37978525, 2023). "The relationship between S100A8/A9 and mortality in sepsis has previously been demonstrated by other studies including larger populations." (PMID 37773186, 2023). "Collectively, these results indicate that S100A8/A9 promotes the development of pulmonary vascular leakage and acute lung injury during sepsis." (PMID 37978525, 2023). "The relationship between plasma S100A8/A9 and cardiac dysfunction was assessed in a cohort of 62 patients with severe sepsis admitted to the intensive care unit of Linköping University Hospital, Sweden." (PMID 37773186, 2023). "We demonstrate that high S100A8/A9 levels are associated with acute LV dysfunction in patients with severe sepsis, and that pharmacologic S100A8/A9 blockade with the small-molecule inhibitor ABR-238901 can mitigate myocardial dysfunction in endotoxemia." (PMID 37773186, 2023). "In the current work, we explored the importance of S100A8/A9 in SIMD and the efficacy of S100A8/A9 blockade with ABR-238901 as a potential treatment in sepsis." (PMID 37773186, 2023). "The ROC analysis demonstrated that plasma S100A8/A9 levels are able to identify sepsis patients with LV dysfunction (c-statistic = 0.694, P = 0.009)." (PMID 37773186, 2023). "In clinical studies, plasma S100A8/A9 was found to be elevated in sepsis patients and to correlate with increased mortality and poor prognosis." (PMID 37773186, 2023). "Due to these important differences, the potential therapeutic effects of S100A8/A9 blockade on cardiac dysfunction in sepsis demonstrated herein cannot be directly extrapolated to the clinical scenario." (PMID 37773186, 2023). "In the context of sepsis, in order to prevent immunosuppression, we advocate maintaining the use of S100A8/A9 blockade to the shortest possible period, until anti-inflammatory effects and cardiovascular stabilization are observed." (PMID 37773186, 2023). "Together with the findings presented herein, these results show broad anti-inflammatory and organ protective properties of S100A8/A9 blockade in the context of endotoxemia and multibacterial sepsis." (PMID 37773186, 2023). "Our findings open the way for future clinical testing or re-purposing of these S100A8/A9 blockers for the treatment of patients with severe sepsis." (PMID 37773186, 2023). "S100A8/9, IL-1, IL-4, and tumor necrosis factor have all been identified in previous research as markers of sepsis-related brain damage in plasma." (PMID 37901226, 2023). "A recent study revealed that sepsis-derived S100A8/A9 induces GSDMD-dependent platelet pyroptosis in severe sepsis by upregulating the TLR4/NLRP3 signaling pathway, which leads to the release of oxidized mtDNA and promotes NETs formation." (PMID 37275856, 2023). "In the early stage of sepsis, endotoxin activates leukocyte, which synthesize and secrete S100A8/A9." (PMID 37978525, 2023).
Sepsis (continued). "S100A8, MMP8, CSF3 and IL-6 protein levels in the peripheral blood of sepsis patients were revealed to be substantially associated with GCS scores following a correlation investigation of the four extracellular molecules with clinical indications (all p<0.05)." (PMID 37901226, 2023). "The present study revealed a previously unidentified crucial function of S100A8/A9 in inducing pulmonary microvascular hyperpermeability and acute lung injury during sepsis." (PMID 37978525, 2023). "Our study identifies S100A8/A9 as an important myocardial depressant factor and a viable treatment target in sepsis." (PMID 37773186, 2023). "S100A9 KO mice were constructed and subjected to CLP to further confirm the involvement of S100A8/A9 in the pathogenesis and development of sepsis." (PMID 37978525, 2023). "ABR-238901 was able to rapidly reverse already established systolic LV dysfunction, which is likely to be present at hospital admission in severe sepsis patients with high S100A8/A9 levels." (PMID 37773186, 2023). "Short-term stimulation (24 hours) of CD34+ HSPCs with sepsis plasma resulted in the up-regulation of these genes and an increase in the fraction of S100A8+ cells in the CD34+ population." (PMID 34103408, 2021). "TNFSF10 (TRAIL) and S100A8/9, were found to be significantly upregulated in late sepsis CD4+ and CD8+ T- lymphocyte subsets, respectively." (PMID 34484194, 2021). "Of note, S100A8 participates in neutrophil chemotaxis and adhesion, and it is up-regulated in patients with sepsis, which is in agreement with the low methylation levels identified in its promoter found in our study." (PMID 33659006, 2021). "When released secondarily during a primary acute inflammatory process like sepsis and infection or autoimmune and autoinflammatory reactions, S100A8/A9 amplifies the primary pro-inflammatory response by activating the MyD88-dependent TLR4 signaling pathway." (PMID 32425933, 2020). "In children and adults, the serum level of S100A8/A9 is clinically used as an excellent biomarker in inflammatory processes like sepsis, rheumatoid arthritis, juvenile idiopathic arthritis, and autoinflammatory diseases." (PMID 32425933, 2020). "Two groups proposed serum S100A8/A9 as a promising sepsis marker in very low birth weight infants respective of infants of all gestational ages." (PMID 32425933, 2020). "The increase in monooxidized S100A8 protein can be explained by the increased production of ROS by neutrophils and monocytes in sepsis or septic shock." (PMID 33425215, 2020). "To examine the physiologic contribution of S100A8/A9 to sepsis, we created an S100A9knockout mouse on a C57BL/6 background." (PMID 29204146, 2017). "Collectively, our data demonstrate that S100A8/A9 significantly contributes to the antimicrobial activity of BM against highly relevant, especially Mn-sensitive, pathogens of sepsis in newborns." (PMID 29326708, 2017). "In contrast, S100A8/A9 proteinrelease from late sepsis Gr1+CD11b+ MDSCsdiminished after LPS stimulation." (PMID 29204146, 2017). "S100A8/A9 mRNAs similarly increasedduring early and late sepsis.Immunoblotting revealed that S100A8/A9 protein levels also increased during earlysepsis and accumulated in late sepsisGr1+CD11b+ cells." (PMID 29204146, 2017). "Vogl and colleagues showed that S100A8/A9 amplifies phagocyte activation during lipopolysaccharide-induced sepsis via activation of TLR-4 upstream of TNF-α response." (PMID 28672877, 2017). "Most recently, we showed that S100A8/A9 was also up regulated in patients with sepsis and correlated with severity of disease." (PMID 25860480, 2015). "As outlined in a previous study, the S100a8/S100a9 plasma levels were significantly elevated in patients with severe sepsis." (PMID 25242054, 2014). "The expression of ApoE, Anxa1, NGAL, S100a8 and S100a9 were all elevated in the progression of sepsis." (PMID 25242054, 2014).
Sepsis (continued). "In conclusion, the present study demonstrated that the expression of five proteins (ApoE, Anxa1, NGAL, protein S100a8 and S100a9) was significantly elevated in the progression of sepsis." (PMID 25242054, 2014). "The present study indicated that the expression of S100a8 and S100a9 were significantly elevated in the lymph during early stages of sepsis (CLP-6h) but decreased in later stages (CLP-24h)." (PMID 25242054, 2014). "S100a8 and S100a9 as members of the S100 protein family, are released from neutrophils and activate phagocytes during sepsis." (PMID 25242054, 2014). "Our findings of increased levels of S100A8/A9 support previous reports of increased expression in other acute and chronic inflammatory conditions including sepsis and septic shock." (PMID 24089588, 2013). "Other indicators of fetal sepsis and/or fetal inflammatory response syndrome were elevated IL-6 and S100A8 in placental tissues." (PMID 22952869, 2012). "In conclusion, the results described here reinforce the central role of MMP-8 in the regulation of neutrophil recruitment to the lungs during sepsis, adding the myeloid-related proteins S100A8 and S100A9 as one of the involved mediators." (PMID 22768176, 2012). "One of these DAMPs, S100A8/A9 is highly expressed in bladder during complicated U. parvum-induced experimental UTI and in serum of patients with sepsis caused by UTI." (PMID 20976233, 2010). "Elevated S100A8 expression exacerbates sepsis-induced organ dysfunction." (PMID 40909263, 2025). "Furthermore, a significant positive correlation exists between elevated S100A8/A9 concentrations and poor clinical outcomes, including increased 28-day mortality in sepsis patients." (PMID 40568710, 2025). "Research has reported higher S100A8 expression in patients with sepsis than in controls." (PMID 40909263, 2025). "Moreover, serum S100A8/A9 levels in sepsis patients show a positive correlation with serum resistin levels." (PMID 40568710, 2025). "Importantly, we identify the persistence of biomarkers such as S100A8/A9, IL-10, mtDNA, and histone lactylation as molecular signatures of a Post-Sepsis Cellular Remnant." (PMID 41007702, 2025). "It has been found that S100A8/A9hi neutrophils induce endothelial mitochondrial dysfunction and PANoptosis (a new type of programmed cell death that combines the features of apoptosis, necroptosis, and pyroptosis) in sepsis." (PMID 40108736, 2025). "Multiple studies have shown that S100A8/A9 plays a vital role in the pathogenesis of inflammatory diseases, including sepsis, myocardial infarction (MI), ischemia/reperfusion, cardiac fibrosis and renal fibrosis; targeting S100A8/A9 effectively improves these diseases and adverse outcomes 10-15." (PMID 40860162, 2025). "We found that S100A8/A9 serves as a predictor of mortality in sepsis patients." (PMID 40568710, 2025). "To unravel the role of S100A8/A9 in sepsis, we integrate scRNA-seq and RNA-seq approaches." (PMID 41303672, 2025). "Inhibitors targeting S100A8/A9 or IL-17, such as anti-S100A8/A9 antibodies or IL-17 inhibitors (e.g., Secukinumab), may help mitigate immune dysregulation and inflammation in sepsis, offering promising avenues for improved patient outcomes." (PMID 41303672, 2025). "Importantly, the predictive value of S100A8/A9 for 28-day mortality was validated in an independent cohort of 55 sepsis patients." (PMID 40568710, 2025). "Additionally, the predictive ability of S100A8/A9 and resistin for sepsis mortality was evaluated using the area under the receiver operating characteristic curve at ICU admission." (PMID 40568710, 2025). "Additionally, sepsis patients with high serum S100A8/A9 concentrations (≥ 377.53 ng/mL) also had a higher survival rate relative to those with lower concentrations (< 377.53 ng/mL)." (PMID 40568710, 2025). "The serum levels of S100A8/A9 and resistin were increased in sepsis patients upon admission." (PMID 40568710, 2025).
Sepsis (continued). "S100A8 has garnered attention as a potential marker for inflammation and sepsis." (PMID 39308854, 2024). "IL-6 and S100A8/A9 are closely related to S. aureus septic arthritis and sepsis in mouse models." (PMID 39204252, 2024). "However, the precise nature of the crosstalk between S100A8/A9 and these signalling pathways in sepsis is yet to be elucidated." (PMID 37978525, 2023). "Our study demonstrates the damaging role of S100A8/A9 in macrophages in sepsis-induced AKI in mice." (PMID 37547329, 2023). "Notably, the key genes upregulated during sepsis are responsible for regulating cell cycle progression and differentiation (i.e., S100A8 and S100A9) and immune responses (i.e., ANXA1, APOBEC3A, LILRA5, CR1, and CD55)." (PMID 37298316, 2023). "A recent study discovered that S100A8/A9 could activate ERK-1/2 signalling by binding to TLR4 in the heart tissues of mice with sepsis." (PMID 37978525, 2023). "In addition, we identified key genes that were upregulated in sepsis, namely, S100A8, S100A9, and CR1, as well as those that were downregulated, namely, CD79A, HLA-DQB2, PLD4, and CCR7." (PMID 37298316, 2023). "In summary, the present study demonstrated a previously unknown role of S100A8/A9 in promoting pulmonary vascular permeability during sepsis." (PMID 37978525, 2023). "However, there is limited knowledge regarding the specific role of S100A8/A9 in regulating pulmonary vascular integrity during sepsis." (PMID 37978525, 2023). "While, the role and mechanism of S100A8/A9 in the genesis of AKI in sepsis is poorly understood." (PMID 37547329, 2023). "This suggests a potential feedback loop where infection-induced neutrophil activation serves as the source of S100A8/A9 secretion in the early stages of sepsis, subsequently activating more neutrophils and increasing the secretion of S100A8/A9, thus perpetuating a vicious cycle." (PMID 37978525, 2023). "However, the precise mechanism by which sepsis induces S100A8/A9 expression in the lungs remains to be elucidated and requires further investigation in future studies." (PMID 37978525, 2023). "S100A8/A9 can regulate neutrophil extracellular trap (NET) formation during sepsis." (PMID 37978525, 2023). "Based on these findings, it was speculated that S100A8/A9 play a crucial role in the disruption of endothelial barrier integrity during sepsis, and targeting the S100A8/A9 function might improve the prognosis of sepsis by improving vascular permeability." (PMID 37978525, 2023). "Our data also highlight that S100A8/A9 may be a new therapeutic target for sepsis-induced liver injury." (PMID 36768433, 2023). "Previous studies have identified elevated S100A8/A9 levels in patients with sepsis and suggested that high plasma S100A8/A9 might be used as a clinical biomarker to grade disease severity." (PMID 37773186, 2023). "Interestingly, during autoinflammatory flares FMF patients share exorbitant high levels of the alarmins S100A8/A9, even higher than controls but also than patients with other AIDs and sepsis." (PMID 38250061, 2023). "The blood levels of S100a8/a9 were correlated to the disease severity in sepsis patients." (PMID 37396347, 2023). "Meanwhile, an increased serum level of S100A8/A9 was demonstrated to correlate with a higher mortality rate in patients with septic shock, as excessive production of S100A8/A9 formed a positive feedback loop exacerbating sepsis-induced hyperinflammation." (PMID 37337301, 2023). "This leads us to believe that blood levels of MMP8 and S100A8 may be valuable biomarkers of sepsis-related brain damage." (PMID 37901226, 2023). "In addition, the plasma concentrations of the S100A8/9 dimer correlated significantly with the MS1 gene expression program in patients with sepsis (Pearson r = 0.51, P < 0.01)." (PMID 34103408, 2021).